ZNF213 (zinc finger protein 213)
Description:
May be involved in transcriptional regulation.
Synonyms: ZKSCAN21; CR53; ZSCAN53
Tractability: No criterion of Open Targets' tractability assessment is met for any kind of drug.
Gene: Protein-coding gene on chromosome 16 (3,129,777 to 3,142,804, forward strand). Ensembl gene ENSG00000085644.
Subcellular location: Nucleus
Subcellular location (Human Protein Atlas): Nuclear membrane; Nucleoplasm; Cytosol; Vesicles
Pathways (Reactome):
Gene expression (Transcription): Generic Transcription Pathway
Gene Ontology:
Molecular function: protein binding; DNA-binding transcription factor activity, RNA polymerase II-specific; RNA polymerase II cis-regulatory region sequence-specific DNA binding
Biological process: regulation of transcription by RNA polymerase II; regulation of DNA-templated transcription
Cellular component: nucleus
Genetic constraint (gnomAD): Loss-of-function variants: 27 observed, 39.24 expected, observed/expected ratio (o/e) 0.69, 90% interval 0.51 to 0.95. The upper end of that interval is the gene's LOEUF score, 0.95, which puts it in group 4 of 6, group 1 being the genes least tolerant of losing a copy. Missense variants: 512 observed, 522.67 expected, observed/expected ratio (o/e) 0.98, 90% interval 0.91 to 1.05. Synonymous variants: 228 observed, 219.35 expected, observed/expected ratio (o/e) 1.04, 90% interval 0.93 to 1.16.
Homologues: Orthologues: macaque ZNF213 (96% identical), chimpanzee ZNF213 (95% identical), guinea pig ZNF213 (83% identical), pig ZNF213 (83% identical), dog ZNF213 (82% identical), rat Zfp213 (76% identical), mouse Zfp213 (75% identical), rabbit ZNF213 (69% identical). Paralogues in human: ZKSCAN1 (37% identical), ZKSCAN3 (37% identical), ZKSCAN4 (37% identical), ZNF263 (36% identical), ZSCAN12 (36% identical), ZSCAN30 (36% identical), ZKSCAN8 (36% identical), ZSCAN21 (36% identical), ZNF394 (35% identical), ZNF165 (35% identical), ZNF397 (35% identical), ZNF500 (35% identical), and 18 more.
Diseases named in the same sentence as ZNF213 in open-access papers:
ZNF213 is named in the same sentence as 5 diseases in open-access papers, as found by Europe PMC text mining. Sharing a sentence is not in itself a finding about the gene and the disease. The quoted sentences say what the papers report.
breast carcinoma (1 paper, 2021). "Since ZNF213 could associate with ER alpha in breast cancer cells, we further investigated the biological effect of such interaction." (PMID 33777799, 2021). "The zinc finger protein ZNF213 modulated ER alpha signaling and breast cancer progression through a post-translational mechanism." (PMID 33777799, 2021). "When it comes to ZNF213, which belongs to zinc finger protein members, we firstly identified its role in breast cancer." (PMID 33777799, 2021). "In summary, our study provided a novel regulatory mechanism between ZNF213 and ER alpha in breast cancer cells." (PMID 33777799, 2021). "In this study, we identified one Zinc finger protein ZNF213, which was higher expression in human breast cancer samples, promoted ER alpha signaling activity and ER alpha stability in breast cancer cells." (PMID 33777799, 2021). "Our study reveals an interesting post-translational mechanism between ER alpha and ZNF213 in breast cancer." (PMID 33777799, 2021). "To analyze the role of ZNF213 in breast cancer cells in an unbiased way, we depleted ZNF213 in MCF-7 cells for RNA sequencing analysis." (PMID 33777799, 2021). "We further investigated the localization of ZNF213 and ER alpha in breast cancer cells." (PMID 33777799, 2021). "Besides, ZNF213 facilitates ER alpha signaling and breast cancer progression via enhancing ER alpha stability." (PMID 33777799, 2021). "ZNF213 depletion inhibited ER alpha signaling and proliferation in breast cancer cells." (PMID 33777799, 2021). "As such an important regulator of ER alpha signaling, ZNF213 could be a promising target for ER alpha positive breast cancer therapeutics." (PMID 33777799, 2021). "ZNF213 is elevated in breast cancers and relates to poor prognosis in endocrine treated patients." (PMID 33777799, 2021). "ZNF213 could be a novel target for ER alpha positive breast cancer patients." (PMID 33777799, 2021). "Targeting ZNF213 could be a promising strategy for breast cancer therapy." (PMID 33777799, 2021). "Targeting ZNF213 could be an appealing strategy for ER alpha positive breast cancer." (PMID 33777799, 2021). "To further validate that ZNF213 is relevant for endocrine resistance, MCF-7 and T47D cells were treated with the indicated tamoxifen concentrations, we found that ZNF213 depletion sensitized tamoxifen inhibition effect in MCF-7 and T47D breast cancer cells." (PMID 33777799, 2021).
cancer (2 papers, 2021 to 2022). A tumor composed of atypical neoplastic, often pleomorphic cells that invade other tissues. "Our study implicated the important role of ZNF213 in ER alpha signaling and improved the understanding of ZNF213 in both genomic and non-genomic regulation in human cancer." (PMID 33777799, 2021). "In previous studies, we characterized several E3 ubiquitin ligases involved in modulating Hippo signaling effectors and cancer progression, such as RNF187 and ZNF213." (PMID 35820928, 2022).
ZNF213 also shares sentences with these, for which no sentence is quoted: adenocarcinoma (1 paper); leukemia (1); triple-negative breast carcinoma (1).